CRP (C-reactive protein)
Diseases named in the same sentence as CRP in open-access papers (continued):
Sharing a sentence is not in itself a finding about the gene and the disease.
COVID-19 (continued). "Other authors also reported increased CRP in COVID-19 patients." (PMID 38421951, 2024). "Interestingly, in another study, in patients with COVID-19 and higher baseline procalcitonin and CRP levels, 32% developed a secondary bacterial infection during their hospital stay." (PMID 38543674, 2024). "Regarding CRP, only case 2 showed levels above the normal range in all the samples tested, suggesting a baseline inflammatory burden heavier than those of the other patients, with a peak of CRP concentration in the first sample after COVID-19." (PMID 39445010, 2024). "Elevated CRP levels predicted COVID-19 mortality in HD patients." (PMID 38807735, 2024). "Various studies showed that elevated CRP levels in COVID-19 patients might indicate excessive inflammatory stress contributing to severe/critical illness or even death." (PMID 38455656, 2024). "The results of this study are consistent with other research, suggesting that corticosteroids may be an effective treatment to mitigate adverse events in COVID-19 patients who exhibit heightened levels of inflammation, as indicated by CRP levels." (PMID 38304653, 2024). "It was found that, except for NLR, LMR, PLR, SAA, and CRP showed no diagnostic value in distinguishing between surviving and non-surviving COVID-19 patients (P > 0.05)." (PMID 39654886, 2024). "Moreover, CRP levels in patients with COVID-19 T2DM significantly differed when compared with control subjects (57.13 ± 2.67 vs. controls 42.4 ± 4.15, p = 0.0029)." (PMID 38675414, 2024). "As reported in the literature, elevated level of C-reactive protein might be an indicator of COVID-19 severity and/or mortality and can be used as biomarker to identify patients’ progression status." (PMID 38206939, 2024). "Both CRP and ferritin are inflammatory markers, and our findings align with other studies that have demonstrated a link between elevated inflammatory markers and poor outcomes in COVID-19 patients." (PMID 39149665, 2024). "It has been seen that severe COVID-19 is characterized by higher levels of some inflammatory biomarkers such as C-reactive protein (CRP), erythrocyte sedimentation rate (ESR), procalcitonin (PCT), and interleukin 6 (IL-6) when compared with mild-to-moderate COVID-19." (PMID 39204242, 2024). "The elevation and role of CRP in COVID-19 is a well-studied topic." (PMID 38626032, 2024). "In conclusion, the study hypothesized that pioglitazone could impact COVID-19-infected patients by reducing inflammatory markers such as IL-3 and CRP." (PMID 39308871, 2024). "Additionally, total and differential leukocyte counts, the neutrophil to lymphocyte ratio (NLR), and C-reactive protein (CRP) and D-dimer values were determined in patients with severe COVID-19." (PMID 38809008, 2024). "Levels of all CE species negatively correlated with C-reactive protein in severe COVID-19 patients." (PMID 39051245, 2024). "Likewise, there was an increase in IL-6 and CRP in COVID-19 patients in comparison with HSs (p ≤ 0.001), and treatment with Vit E decreased their levels (p ≤ 0.001)." (PMID 39057070, 2024). "To explore the association between inflammation and hyperglycemic crises during the infection of COVID-19, we performed ROC analysis and found that CRP and PCT exhibited high power of discrimination for DKA or HHS, with the area under curve (AUC) of 0.723 and 0.794, respectively." (PMID 38455656, 2024). "Corticosteroid use has been associated with statistically significant lower levels of CRP compared with no corticosteroid use in patients with COVID-19." (PMID 38543674, 2024). "Higher levels of IL-6 and CRP were found in numerous studies as markers of COVID-19 severity." (PMID 38686386, 2024). "We also observed nominally significant effects of CRP levels on severe COVID-19." (PMID 39062668, 2024).
COVID-19 (continued). "Despite the clinical manifestation, different findings such as changes in leukocyte count, lymphopenia, decrease in absolute neutrophil count, and elevated levels of C reactive protein (CRP) have been seen in the primary laboratory investigation of patients diagnosed with COVID-19." (PMID 38515718, 2024). "Similarly, male patients with mild-to-moderate COVID-19 exhibited a higher incidence of lymphopenia (16.79% ± 10.42%) and elevated CRP levels (93.32 ± 73.33 mg/L) compared to females (21.08% ± 12.61% and 64.09 ± 65.22 mg/L), respectively." (PMID 38750426, 2024). "CRP is another biomarker with increased level in COVID-19 patients." (PMID 39335569, 2024). "Based on the findings of our study, DNA damage, demographic characteristics (age, sex, and BMI), and laboratory parameters (CRP, INR, and creatinine) could identify people at high risk of severe COVID-19." (PMID 39408623, 2024). "In the group of patients with COVID-19, a significant relationship was found between CRP and FVC." (PMID 39335569, 2024). "Additionally, in a time-to-mortality Cox regression analysis, a threshold cutoff of CRP ≥ 40 mg/L demonstrated good performance in predicting COVID-19 mortality." (PMID 38467760, 2024). "Additionally, neutrophils, lymphocytes, eosinophils, CRP, and radiological manifestations of COVID-19 are correlated." (PMID 39188873, 2024). "A valuable marker to predict the possibility of aggravation of mild forms of COVID-19 to severe forms could be elevated CRP." (PMID 38361692, 2024). "The variables included in the multivariate model represented components of the pathophysiological triad characterizing the acute phase of severe COVID-19: hemodynamic compromise (systolic blood pressure), respiratory failure (oxygen saturation), and systemic inflammation (CRP)." (PMID 39536208, 2024). "Previous studies have shown that factors such as male, older age, comorbidities, medical history, white blood cell count, serum creatinine, C-reactive protein, and erythrocyte sedimentation rate increase the hospitalization and mortality rates of COVID-19 patients 16-20." (PMID 38169716, 2024). "In conclusion, higher levels of the biomarkers CRP, IL6, IP10, ferritin, IFNα, IL8, IL1RA, MCP1, and lower levels of RANTES measured within 7 days of symptoms onset were associated with increased risk of hospitalization due to COVID-19 progression." (PMID 39664394, 2024). "However, there are few studies on the correlation between the serum C-reactive protein (CRP) and cancer patients with COVID-19." (PMID 38215120, 2024). "Adding active vitamin D to the COVID-19 treatment regimen in our setting reduced the PSI at discharge when patients either required supplemental oxygen or high-dose corticosteroid therapy or had a high CRP concentration (> 30 mg/L) at treatment initiation." (PMID 38383361, 2024). "It has been reported that exposure to nephrotoxic drugs, high C-reactive protein (CRP), increased white blood cell (WBC) counts, and low serum albumin levels may be risk factors for AKI in children with COVID-19." (PMID 39031240, 2024). "Cholesteryl ester species negatively correlated with CRP in severe COVID-19 patients." (PMID 39408818, 2024). "This study clearly demonstrated the relationship between CRP level and COVID-19 severity." (PMID 38698064, 2024). "Flea-borne typhus and COVID-19 may also have similar laboratory abnormalities, including elevated ferritin, C-reactive protein, and D-dimer." (PMID 38384261, 2024). "Published results comparing CRP levels between LongC and those people recovered from COVID-19 vary." (PMID 38534322, 2024). "IL-34 levels increased in correlation with CRP in predicting the diagnosis of COVID-19." (PMID 38626032, 2024). "Our research also finds that IL-6 and CRP is significantly increased, suggesting that inflammation may be one of the mechanisms contributing to myocardial harm in cases of COVID-19." (PMID 38706946, 2024).
COVID-19 (continued). "The maximum CRP value and CRP increase rate can also predict COVID-19 severity." (PMID 38263011, 2024). "CRP, IL6, and IP10 could support clinical decision making, particularly the need of referral or admission, by identifying high-risk COVID-19 patients in an outpatient setting or emergency service." (PMID 39664394, 2024). "CRP was significantly related to severity of COVID-19 patients." (PMID 39931433, 2024). "In one study, in patients with COVID-19-associated thrombotic events, no statistical significance was recorded between serum levels of inflammatory markers (CRP, ferritin), age, and other clinical characteristics, except for IL-1β and soluble P-selectin." (PMID 36979908, 2023). "However, remarkably, the COVID-19-related parameters of cluster 2 are much better: low CRP and high O2 saturation (this variable was reversed, so a high value in the plot means low O2 saturation)." (PMID 37258639, 2023). "Additionally, our study demonstrated that there was a significant increase in CRP, ferritin and D-dimer in severe and moderate COVID-19 patients compared with controls and in CRP and ferritin in severe COVID-19 patients compared to moderate COVID-19 patients." (PMID 37653506, 2023). "Moreover, the higher levels of biomarkers for the diagnosis and monitoring of COVID-19 (e.g., D-dimer, C-reactive protein [CRP], lactate [LDH], and ferritin) suggested that IR_cluster2 patients showed more severe disease." (PMID 37932287, 2023). "The loss of butyrate-producing anti-inflammatory bacteria (e.g., Faecalibacterium and Roseburia) as well as the upregulation of proinflammatory mediators (e.g., CRP, IL-6 and soluble IL-2 receptor (sIL2R)) was more pronounced in severe/critical COVID-19 patients than mild patients." (PMID 37205106, 2023). "Additionally, infants with COVID-19 were 2.5 times more likely to have an inflammatory syndrome characterized by elevated C-reactive protein levels compared to those with RSV infection (p = 0.007, OR = 2.6)." (PMID 38257763, 2023). "In the Immunological subtype, COVID-19 began with abnormally low systolic blood pressure, followed by a cascade of decreases in lymphocyte and platelet count and then elevated temperature, heart rate and CRP levels at more advanced disease." (PMID 37339958, 2023). "Furthermore, patients with COVID-19 who exhibit elevated CRP levels upon admission are more likely to experience hypoxia and respiratory failure than others." (PMID 37520482, 2023). "CRP and C4 had an insignificant positive association with bacterial pneumonia and an insignificant weak negative correlation with COVID-19." (PMID 38585537, 2023). "Elevated CRP serum levels in COVID-19 patients might indicate excessive inflammatory stress contributing to severe/critical illness or even death." (PMID 37484181, 2023). "Compared to patients with unfacilitated ED reattendances, patients with facilitated reattendances had a higher mean CRP (53.63 vs 41.67 mg/L), later median day of COVID-19 illness (8 vs 7 days) and higher percentage likelihood of being non-white ethnicity (32% vs 21%)." (PMID 37437035, 2023). "In severe cases of COVID-19, an elevated CRP level is closely related to mortality." (PMID 37111389, 2023). "A study reported that 2601 (93.5%) of 2782 COVID-19 patients over the age of 18 years had high Hs-CRP rates and in the presence of CRP found above the median value, more severe infections, such as venous thromboembolism and pneumonia, were found in the COVID-19 patients." (PMID 36867280, 2023). "Another study conducted by Novacescu and his team, with a focus on using therapeutic plasma exchange followed by convalescent plasma transfusion in severe and critically ill COVID-19 patients, observed a significant decrease in CRP in the treatment group with an increase in survival days." (PMID 37763241, 2023).
COVID-19 (continued). "For the same reason, the observed associations of CRP serum concentration and PP aggregates with COVID-19 severity did not translate into a correlation between the two parameters." (PMID 37935793, 2023). "The immune patterns of COVID-19 include lymphopenia, lymphocyte activation and dysfunction, increased production of cytokines, especially of IL-1β, IL-6, and IL-10, increased IgG antibodies as well as elevated levels of C-reactive protein (CRP)." (PMID 37483591, 2023). "The combination of lymphocyte count and CRP as a single biomarker may therefore provide a more comprehensive assessment of the overall inflammatory response in acute COVID-19." (PMID 37373898, 2023). "The results of this investigation showed that various COVID-19 severity biomarkers, including ferritin, C-reactive protein, and lactate dehydrogenase, may improve more quickly with RDV treatment." (PMID 38024833, 2023). "In all four patients, the indication for a PET/CT was persistent elevation of CRP and the leucocyte count, accompanied by a deterioration in respiratory and/or vital functions in the post-acute phase of their COVID-19 ARDS (between day 18 and 37 after intubation)." (PMID 37275950, 2023). "Their review consistently highlighted age, CRP levels, lymphocyte counts, LDH levels, and findings in chest X-rays and CT scans as the most commonly reported indicators linked to a poor outcome in COVID-19 patients." (PMID 38005862, 2023). "who reported elevated levels of CRP in long COVID-19 patients." (PMID 37398656, 2023). "The trends of IL6, CRP, and hs-TnI were analyzed in COVID-19 patients with myocardial injury." (PMID 37564653, 2023). "Shah and colleagues reported a significant reduction of SDNN and rMSSD in women and men recently recovered from COVID-19 (30–45 days after an acute infection) and suggested that alterations of rMSSD were inversely correlated to inflammatory markers CRP and interleukin-615." (PMID 37739977, 2023). "CRP increased particularly in 75-93% of severe COVID-19 patients." (PMID 36843786, 2023). "Of note, elevated CRP levels can facilitate the early detection of oxidant–antioxidant levels and necessitate specialized attention for individuals in critical condition with COVID-19." (PMID 37628401, 2023). "Multiple and logistic regressions selected the following risk predictors for pneumonia as IL-6, CRP, obesity and for severe COVID-19 symptoms D-dimer level and a lack of targeted vaccination (p < 0.001)." (PMID 37608339, 2023). "Easy-to-access biomarkers such as CRP, neutrophilia, and HbA1c may play a significant role in informing clinical management to prevent high mortality due to COVID-19 in PLWH at the district-level hospitals." (PMID 36855103, 2023). "The dendograms were built based on the clustering metric “Euclidean” and the method “complete,” in which we found the following 9 neighboring factors around COVID-19 severity: D-dimer, fibrinogen, CRP, LDH, WBC count, number of neutrophils, glucose, scoring index of chest x-ray, and ferritin." (PMID 36668902, 2023). "C-reactive protein (CRP) was used as leading biomarker as this biomarker was used in nearly all studies on tocilizumab; it reflects inflammation, and was shown to be prognostically predictive in COVID-19." (PMID 37278822, 2023). "Moreover, in addition to CRP, D-dimer has been another blood marker that can be elevated in COVID-19 and has proven to prognosticate adverse outcomes accurately." (PMID 36814202, 2023). "There was a strong association between C3 and CRP in patients with bacterial pneumonia (R=0.591; P<0.001) and a weak negative correlation with COVID-19." (PMID 38585537, 2023). "Furthermore, a prospective study found that treatment with dexamethasone and tocilizumab significantly decreased PCT and CRP values, thereby limiting their ability to track the presence of secondary infections in COVID-19 ICU patients." (PMID 37107071, 2023).
COVID-19 (continued). "The abnormal immune cell subsets, the increased inflammatory cytokines, and the augmented CRP levels show the patient’s inflammatory state after ten days of getting the COVID-19 mRNA COVID-19 vaccine, which may trigger cardiac injury and dysfunction." (PMID 37661270, 2023). "These investigators stated that also changes in CRP could provide reliable information in the Omicron COVID-19 diagnosis." (PMID 37110348, 2023). "Only the CT% and serum CRP were higher in severe compared to moderate COVID-19." (PMID 37373331, 2023). "Both were elevated in COVID-19 positive and COVID-19 negative sepsis patients, supporting previous findings by Traby and co-workers, who reported elevated levels of citrullinated histone H3, D-dimer, CRP, IL-6, as well as an increased neutrophil-to-lymphocyte ratio in COVID-19 patients." (PMID 36980378, 2023). "Both IL-6 and CRP levels were increased in COVID-19 patients compared to healthy controls." (PMID 37051252, 2023). "After the intervention, the CRP concentration was significantly reduced in the severe and moderate COVID-19 groups and the control group in response to multi-professional intervention, a factor that reinforces the effectiveness of physical exercise in reversing the inflammatory process." (PMID 37700761, 2023). "Most patients with severe COVID-19 showed a CRP > 5 mg/dl (100%) and/or Lymphopenia described as lymphocyte < 800 cells/mm2 (91%) (OR for severe COVID-19: 1.4, 95, CI: (1.1–1.6) CPR > 5 mg/dl vs. CRP > 5 mg/dl; p = 0.043; 1.3, 95, CI: (1.1–2) Lymphopenia vs. non-lymphopenia; p = 0.047)." (PMID 38993895, 2023). "Of note, CRP and ESR were not obtained from healthy controls or COVID-recovered individuals, and the inability to detect a statisfically significant difference despite an upward trend in CRP across COVID-19 severity may be a result of limited sample size." (PMID 37425266, 2023). "They further display that CRP kinetics retains an acceptable infection predictive value and should be promptly considered in conjunction with relevant clinical assessment and microbiological culture collection in septic COVID-19 patients." (PMID 37834754, 2023). "According to the guidelines, CRP, an inflammatory marker, must be assessed in COVID-19 patients." (PMID 37654997, 2023). "Patients with higher CRP, LDH, ferritin and fibrinogen levels had a higher risk of being admitted to the intensive care unit and dying, which makes it vital to foresee the course of COVID-19." (PMID 36843786, 2023). "In addition, inflammatory indicators – CRP and hospital stay were included to analysis, which can further reflect the course of COVID-19 patients." (PMID 37284648, 2023). "Both studies considered CRP levels as a strong indicator of the presence and severity of COVID-19." (PMID 36968904, 2023). "Our findings imply that CRP may be a biomarker of ICU referral, as well as death in COVID-19 patients, emphasizing the need of regularly monitoring CRP changes." (PMID 36747045, 2023). "Negative likelihood ratios indicate that IL-6, PCT, and CRP at hospital admission can be used for identifying patients at low risk for severe COVID-19 progression." (PMID 37937220, 2023). "Significant differences in cytokine levels (e.g., IL-6) and plasma protein levels (e.g., C-reactive protein, CRP) were reported among different groups of COVID-19 patients, and both indices were considered potential biomarkers for the diagnosis, progression, and prognosis of COVID-19." (PMID 37894092, 2023). "In COVID-19 patients, the CRP level may be higher than normal 6–8 hours after the onset of first symptoms and may reach its peak level in 48 hours." (PMID 37127269, 2023). "CRP may be a rapid, widely available, useful predictive factor for determining the severity of COVID-19 patients." (PMID 37284648, 2023). "Therefore, it is crucial to closely monitor liver enzymes and CRP levels in COVID-19 patients, especially those with pre-existing liver conditions." (PMID 37363445, 2023).